CD44 (CD44 molecule (IN blood group))
Diseases named in the same sentence as CD44 in open-access papers (continued):
Sharing a sentence is not in itself a finding about the gene and the disease.
breast carcinoma (continued). "In contrast to the differential CD47 expression profiles, we did not observe a significant difference of CD44 protein levels between the exosomes from the healthy control group and those from the breast cancer patients." (PMID 27819324, 2016). "Several investigators have shown that CD44+/CD24− cell staining is not an entirely consistent indicator of tumor initiating ability in ER−/PR−/Her2− breast cancer cells due to over-staining of TNBCs." (PMID 26984638, 2016). "Tumor-initiating breast cancer cells can be distinguished from the non-tumorigenic cancer cells based on presence of the CD44+CD24−/low phenotype." (PMID 26595803, 2016). "High levels of CD44 and low levels of CD24 induce stem-like activities in breast cancer cells." (PMID 27713506, 2016). "With respect to these markers, thyroid cancers are similar to other malignancies in terms of expression of CD44+CD24−, ALDH+, and CD133+ (breast cancers), CD133+ and ALDH+ (colon cancers), and CD44highESAlow-EMT and CD44highESAhigh-EMT in oral squamous cell carcinomas (see Ref." (PMID 26973599, 2016). "Furthermore, the chemo-tolerant subpopulation in both basal-like and luminal breast cancer cell lines co-express both an epithelial marker CD24 and a mesenchymal marker CD44, indicating its hybrid E/M status." (PMID 27008704, 2016). "Specifically reagrding the corrleation between the CD44+/CD24low/ sub-population and metastatic dissemination in Luminal-A breast cancer patients, not many reports are available." (PMID 27835603, 2016). "Functional evaluation was performed in MDA-MB-231 breast cancer cells that fit the basal subtype, in which CD44+/CD24− cells are enriched and no therapy is available." (PMID 27009862, 2016). "Studying tumorigenic cells separated in vitro, from malignant human breast cancer-derived pleural effusions, Al Hajj and colleagues isolated a cell population characterized by high CD44 expression and low or undetectable levels of CD24 (CD44+/CD24−/low)." (PMID 26757880, 2016). "Breast cancer stem cells are classically defined by CD44 (Cluster of Differentiation antigen-44) positive and low or absent levels of CD24 (Cluster of Differentiation antigen-24) expression (CD44+/CD24−/low)." (PMID 27876836, 2016). "Recent study report that, the proportion of the CD44+/CD24− CSCs were significantly increased in the specimens treated with neoadjuvant chemotherapy compared with paired breast cancer biopsy specimens without chemotherapy." (PMID 26556875, 2015). "We measured the mRNA levels of CD44 and 17 kDa cleaved CD44ICD respectively by RT-PCR and western blot analysis, as well as by evaluating their surface expression using a FACS analysis in six breast cancer cell lines." (PMID 25909162, 2015). "The close correlation between CD44 and EGFR expressions may be another reason for the resistance to EGFR inhibitors in breast cancer." (PMID 25429827, 2015). "Whereas the CD44 surface expression was detected in five cell lines but not in ZR-75–1 cells, among the six breast cancer cell lines, cleaved CD44ICD was strongly detected in the MCF-7, T47D, JIMT and MDA-MB-231 cell lines." (PMID 25909162, 2015). "In primary mammary carcinomas hypoxia increases the proportion of CD44+CD24−/lowESA+ CSCs in tumors that have low levels or no active ER signaling, according to their ER and PR expression levels detected by immunohistochemistry." (PMID 26372732, 2015). "Not surprisingly, neutralizing antibodies targeting CD44 effectively inhibited tumor growth and prevented tumor relapse after chemotherapy-induced remission in an orthotopic xenograft model of human breast cancer." (PMID 26322272, 2015). "It is not surprising that our Py230 luminal MaCSCs do not express CD44, a marker commonly used to identify breast cancer stem cells that give rise to aggressive triple-negative breast cancers." (PMID 26467658, 2015).
breast carcinoma (continued). "Confocal imaging revealed an enhanced membrane expression of CD44 and CD24 in the DTCs derived from the basal-like breast cancer cell line MDA-MB-468 as compared with treatment-naive parent cells, which was validated using fluorescence-activated cell sorting (FACS)." (PMID 25669750, 2015). "Importantly, CD44+CD24−/lowESA+ cells, ALDH+ cells and mammosphere-forming cells isolated from breast cancer cell lines are also enriched for self-renewal capacity and tumorigenic potential in xenograft tumor assays." (PMID 26372732, 2015). "In human primary breast cancer xenografts, total and phosphorylated IGF1R expression is significantly higher in the CD44+CD24− sorted breast cancer stem cell population compared to the non-CD44+CD24− population." (PMID 25964777, 2015). "After anti-CD44 antibodies were conjugated, the targeted biotin-MBs could successfully attach to the target MDA-MB-231 breast cancer cells and be used to separate these cells from the single-cell-type suspension." (PMID 25993512, 2015). "Without dispute is evidence in breast cancer that CD44 is expressed by primary tumors, in regional lymph node metastases, and early disseminated “stem-like” tumor cells within the bone marrow of patients." (PMID 25888636, 2015). "Similar stories hold true for CD133 in glioblastoma and for CD44 and ALDH+ in breast cancer." (PMID 26452033, 2015). "A recent study of a mouse mammary epithelial cell line (NMuMG) and a triple negative human breast cancer cell line MDAMB231 shows that CD44 couples with VCAM-1 in order to initiate EMT as well as chemoresistance." (PMID 25954275, 2015). "We also find that IL-6 mRNA levels are readily detected ex vivo only in CK-5 positive basal-like breast carcinoma tissues, an uncommon form of biological aggressive breast carcinoma with stem-cell-like features, including high levels of CD133 and CD44 expressions." (PMID 25881039, 2015). "Here, we demonstrated that CD44 was activated on breast cancer cells but was inactive on normal cells in vitro and in vivo." (PMID 25909172, 2015). "Expression of MT1-MMP or CD44 in a breast cancer cell line alone did not stimulate cell migration, but coexpression did." (PMID 26091717, 2015). "Furthermore, the establishment of aggressive breast cancer phenotype following upregulation of NEDD9 is accompanied by increased expression of serglycin, its cell surface binding partner CD44, and CS synthesizing enzymes." (PMID 26581653, 2015). "Our study suggested that the active state of CD44 plays a crucial role in the selective targeting of breast cancer cells by avoiding nonspecific toxicity to CD44-quiescent normal cells." (PMID 25909172, 2015). "Because the targeting of CSCs has been viewed as an important strategy for long-lasting treatment, a number of studies have focused on the identification of CSC markers such as CD44, CD24, epithelial cell surface antigen (ESA), and aldehyde dehydrogenase 1 (ALDH1) in breast cancer." (PMID 26528725, 2015). "On purified mammospheres by clonal selection, CD44, the most consistently used biomarker, together with Cd24low, to identify and characterize the breast cancer stem cell (BCSC) phenotype, was also measured by cytofluorimetry, indicating that about 90% of the purified stem cells were CD44+." (PMID 26517518, 2015). "In these studies, the subpopulation of CD44+/CD24−/low cells, enriched for CSCs, of two breast cancer cell lines and the primary culture of patient breast cancer cells, demonstrated enhanced expression of phosphorylated ATM after radiation, which correlates with increased radioresistance." (PMID 24681585, 2014).
breast carcinoma (continued). "We found that SC35 induced the expression of the C5-V6-C6 isoform of CD44, which was not significantly expressed in the non-metastatic breast cancer cell line MCF-7." (PMID 24173428, 2014). "This indicates that expression of CD44 in breast cancer cells confers iota toxin resistance by inhibiting endocytosis, a role not previously defined for CD44." (PMID 24990559, 2014). "From the perspective of a protein-based treatment tool, C. perfringens iota toxin is relatively unexplored yet possesses promising potential for targeting breast cancer, as recent evidence now implicates LSR and CD44 as functional facilitators of iota cytotoxicity." (PMID 24990559, 2014). "Breast cancer cell line (MCF7) was labelled and sorted into two populations CD44+/24lo/ESA+ (Stem-like cells) and CD44-/24hi/ESA- (Non stem-like cells) and according to cell cycle (Hoechst DNA profile) within the two populations into G0/1 and S/G2/M, and for comparison the whole cell population." (PMID 25277201, 2014). "Recovery of CD44 and its binding partners from raft versus non-raft membrane microdomains was profiled in non-migrating and migrating breast cancer cell lines." (PMID 24512624, 2014). "This suggests that it is possible to achieve a therapeutic effect without a complete repression of CD44 and has an impact on future development of breast cancer treatment." (PMID 25184276, 2014). "In a parallel experimental set using the razor-wound migration assay method, human breast cancer cell line MCF-7 furnished higher expression of CSC-markers (that is, CD44+/CD24-/low) in the migrating population as compared with the non-migrating fraction of cells as evident from our confocal data." (PMID 25315241, 2014). "Clearly, CD44+CD24− CSC had stronger tumorigenicity, which may contribute to breast cancer recurrence." (PMID 25301732, 2014). "Thus, CD44 expressed by TIME cells is crucial for regulation of both the early and late adhesion of breast cancer cells." (PMID 24614402, 2014). "Flow cytometric identification of CD44high/CD24low cells is a useful measure of BCSCs in luminal-type breast cancer but not in basal-like breast cancer cell lines, which express CD44 at high levels." (PMID 25587023, 2014). "In human breast cancer, putative cancer stem cells were first isolated by the expression pattern of cell surface makers, CD44 and CD24, and the breast cancer cells with a CD44+/CD24−/low phenotype were able to form tumors in immunodeficient mice with a very low number of cells." (PMID 25229616, 2014). "Whereas a physical interaction between CD44 and HYAL2 has been demonstrated in breast cancer cell line MDA-MB-231 and rat v-Src-transformed fibroblasts, we were unable to demonstrate such an interaction in TIME cells using co-immunoprecipitation (data not shown)." (PMID 24614402, 2014). "In addition, repression of NF-κB target genes, e.g., CD44 and possibly other genes (e.g., BCL-XL, cMyc, and MMP9), decreased proliferation and invasiveness of breast cancer cells." (PMID 25184276, 2014). "Similar to observations of cancer stem cell phenotypes in hematopoietic malignancies, CD44+/CD24lo is not a universal marker of cancer stem cells in breast cancer." (PMID 25080108, 2014). "Since the CD44+/CD24-/low antigenic phenotype does not constitute a universal antigenic phenotype of TICs in all breast cancer subtypes, it is necessary to identify novel TIC markers in order to better define this phenotype." (PMID 25216750, 2014). "To test whether STAT3 drives the stem cell phenotype in breast cancer cells, we knocked down STAT3 gene by shRNAs and examined the CD44+ subpopulation by fluorescence activated cell sorting (FACS)." (PMID 24297508, 2014). "Collectively, these data suggest that expression of LSR and not CD44 is required for sensitivity of breast cancer cells to iota toxin." (PMID 24990559, 2014).
breast carcinoma (continued). "Utilizing markers of breast cancer stem cells we demonstrate that the ALDH+ and ALDH+/CD44+/CD24− subpopulations of breast cancer cells express higher levels of P-STAT3 (Y705) compared to the un-separated, ALDH−, or ALDH−/CD44+/CD24− subpopulations." (PMID 24376586, 2013). "In addition, we observed that LLL12 inhibited cell viability and tumorsphere forming capacity in the ALDH+/CD44+/CD24+ subpopulation of MDA-MB-231 and SUM159 breast cancer cells." (PMID 24376586, 2013). "A recent study reported that CD44+ tumor-initiating breast cancer cells had preferential activation of STAT3, suggesting that STAT3 may be a potential therapeutic target in breast cancer." (PMID 23326564, 2013). "Furthermore, the CTCs identified in the breast cancer patients BC1 and BC5 showed high-level expression of CD44 and ALDH1, respectively." (PMID 24019862, 2013). "CD44 and MUC-1 are already known to be Tn-positive proteins in breast cancer." (PMID 23637900, 2013). "When used to evaluate tumor initiation of common breast carcinoma cell lines, the percentage of CD44+/CD24- did not correlate to tumorigenicity, it does, however, correlate strongly with rare basal and mesenchymal phenotype." (PMID 24124614, 2013). "In vitro, Ca1a, MCF7, Sum159, and MDA-MB-231 breast cancer lines, sorted CD44+CD24+ non-invasive cells could give rise to invasive CD44+CD24− cells (and vice versa), even when initially plated as single cell clones." (PMID 23986719, 2013). "The JAK2/STAT3 signaling pathway is preferentially activated in CD44+ breast cancer stem cell population over other cell populations, and hyaluronic acid synthase 1 (HAS1) is a STAT3 signaling-related molecule in basal-like breast cancer." (PMID 23326564, 2013). "Reports from others demonstrate that Notch4 signaling is elevated in CD44+/CD24− cells and that inhibiting this pathway reduces mammosphere formation and prevents tumor initiation in vivo identifying Notch4 as a critical regulator of breast cancer TICs." (PMID 23593654, 2013). "In view of the reported involvement of IGF-1R signaling in the metastasis and epithelial-mesenchymal transition (EMT) of breast cancer cells, we further investigated whether IGF-1R signal also regulates EMT process in CD44+ BCSCs." (PMID 23663564, 2013). "Moreover, CD44+CD24low+ cells in both MDA-MB-231 and DT-22 showed greater motility and invasion, and preferential expression of gene profiles observed in breast cancers metastatic to lung or brain and that characterize bone metastasis." (PMID 23982961, 2013). "Hyaluronan, CD44 and another hyaluronan receptor, receptor for hyaluronan mediated motility (RHAMM) have been shown to form signaling complexes with extracellular regulated kinase 1/2 (ERK1/2), leading to increased motility of breast cancer cells." (PMID 23560496, 2013). "In normal adjacent tissue from women with ER+ breast cancer, 15 out of 45 were positive for the stem cell-like gene expression profile without expression of CD44+CD49f+CD133/2+." (PMID 24008095, 2013). "Other authors have detected a CD44+/CD24- phenotype in 91.9, 93.0, 76.2, and 44.3% of four different cell lines from canine mammary neoplasms using flow cytometry, however the immunohistochemical expression of these proteins was not demonstrated in canine mammary neoplasms." (PMID 24119896, 2013). "Specific cell surface markers for CSCs have been detected in human mammary neoplasms which stain positive for CD44 and negative or low for CD24." (PMID 24119896, 2013). "We found that the proportion of CD44+/CD24- tumor cells was similar in breast cancer samples with and without basal-like features (11.93% versus 18.44%, p = 0.143)." (PMID 22762532, 2012).
breast carcinoma (continued). "In corroborating work, targeting the SH2 domain of Stat3 with a novel small molecule decreased the percentage of cells expressing TIC markers (CD44+/CD24−/low and ALDH+) and mammosphere formation in p-Stat3 overexpressing human breast cancer xenografts in SCID-beige mice." (PMID 22879872, 2012). "The relevance of this marker combination has been confirmed for breast tumor cells lines, although the percentage of putative CD24−/CD44+ breast cancer tumorsphere TICs did not correlate with tumorigenicity." (PMID 23042145, 2012). "Using a three-dimensional clonogenic assay of tumor cells, Sartorius' group determined that ER–, PR–, CD44+ and CK5+ cells should be defined as breast cancer stem cells according to their capacity to produce more differentiated cells, the majority of which are ER+, PR+, CK–." (PMID 23554768, 2012). "Analysis of differences between CD44+/CD24− and breast cancer subtypes." (PMID 23028444, 2012). "For example, Gupta and colleagues utilized a chemical screen to identify drugs with selective toxicity for BCSCs and found that salinomycin was able to reduce the prevalence of CD44+/CD24− BCSCs compared to paclitaxel, a commonly used breast cancer chemotherapeutic agent." (PMID 24977105, 2012). "Our lab has observed increased tumorigenicity and metastatic ability to the lung of stem-like ALDHhi CD44+ stem-like breast cancer cells relative to nonstem-like ALDHlow CD44− cells." (PMID 22295241, 2012). "In fact, human breast cancer cells strongly expressing CD44 along with low or no expression of CD24 effectively formed tumors." (PMID 22400115, 2012). "Tumorigenic breast cancer cells that express high levels of CD44 and low or undetectable levels of CD24 (CD44+/CD24-/low) may be resistant to chemotherapy and therefore responsible for cancer relapse." (PMID 22839505, 2012). "We examined gene expression datasets to determine the breast cancer subtypes with Six1 overexpression, and then examined its expression in the CD24low/CD44+ putative TIC population in human luminal breast cancers xenografted through mice and in luminal breast cancer cell lines." (PMID 22765220, 2012). "Most of these conserved TFBSs involved in breast cancer (e.g., AP-1, NFκB, and STAT5), stem cells and embryonic development (e.g., OCT1, PAX6, GATA1), and therefore had the highest potential for regulating CD44 and for being involved in breast cancer." (PMID 23226410, 2012). "Expression of CD44, CD24, and E-selectin ligands on human breast cancer cell lines." (PMID 22934288, 2012). "Previously studies have been confirmed that breast cancer contains a CSC-compartment, which can be enriched by purifying Aldehyde dehydrogenase 1 (ALDH1)-positive cells or CD44+/CD24−/low cells by sorting, and also by purifying sphereforming cells (mammospheres) from parental cells." (PMID 22761812, 2012). "The morphology of tumors in WT mice derived from MMT mouse lung tissue cells resembled the primary mammary tumors in MMT mice (data not shown) as well as grafts of CD44+ tumor cells into WT mice." (PMID 22277639, 2012). "Stimulation of breast cancer cells with TGFβ results in co-localization of the matrix metalloproteinase MT1-MMP and CD44 at the cell membrane and induces CD44 cleavage resulting in high levels of soluble CD44." (PMID 22069487, 2011). "The phenotype of CD44+/CD24- in breast cancer cells exhibits a higher potential compared to other phenotypes of breast cancer cell lines, however, this is not sufficient evidence to elucidate the relationship with pulmonary metastasis." (PMID 21749678, 2011). "In human breast cancer cell lines, it has been found that an ALDEFLUOR-positive CD44+ subpopulation of CD133+ cells was more enriched for tumor-initiating cells than ALDEFLUOR-negative CD44−/CD133+ cells." (PMID 21264259, 2011).